RNU7-81P (RNA, U7 small nuclear 81 pseudogene)
Synonyms: U7.81
Gene: Small nuclear RNA gene on chromosome 2 (54,850,289 to 54,850,352, forward strand). Ensembl gene ENSG00000252507.
Homologues: Orthologues: chimpanzee U7 (97% identical), macaque U7 (89% identical). Paralogues in human: RNU7-40P (84% identical), RNU7-49P (83% identical), U7 (83% identical), RNU7-113P (81% identical), RNU7-2P (81% identical), RNU7-43P (81% identical), RNU7-48P (81% identical), RNU7-62P (81% identical), RNU7-73P (81% identical), RNU7-11P (80% identical), RNU7-14P (80% identical), RNU7-25P (80% identical), and 142 more.